ENSG00000285932 (novel transcript)
Gene: Protein-coding gene on chromosome 10 (99,651,595 to 99,732,112, reverse strand). Ensembl gene ENSG00000285932.
Genetic constraint (gnomAD): Missense variants: 175 observed, 238.72 expected, observed/expected ratio (o/e) 0.73, 90% interval 0.65 to 0.83. Synonymous variants: 76 observed, 87.34 expected, observed/expected ratio (o/e) 0.87, 90% interval 0.72 to 1.05.